PLK1 (polo like kinase 1)
Diseases named in the same sentence as PLK1 in open-access papers (continued):
Sharing a sentence is not in itself a finding about the gene and the disease.
tumor (continued). "The Cas9-mediated knockout of the Plk1 gene in the tumor in an orthotopic GBM mouse model effectively suppressed tumor growth, significantly improved the median survival time of mice from 18 days (PBS-treated) to 40 days, and meanwhile had negligible side effects." (PMID 37485250, 2023). "The combined pharmacological inhibition of ACLY and PLK1 may inhibit pan-tumor cell proliferation through UBE2C to achieve a “triple win”." (PMID 37958642, 2023). "Moreover, the study revealed that high expression of PLK1 had a poor prognosis in 11 tumor types, including KIRC, KIRP, etc., while high expression of KLF9 was associated with a better prognosis in KIRC." (PMID 37000317, 2023). "Finally, the impact of silencing PLK1 on the growth of transplanted tumors was explored via transplantation tumor assay in nude mice." (PMID 37744268, 2023). "It was reported that cRGD-modified iLNPs could interact with HepG2 cells more efficiently than unmodified counterparts, which dramatically enhanced antitumor efficacy of PLK1 siRNA in tumor-bearing mice." (PMID 38516300, 2023). "Moreover, in NB and SCLC, MYCN-amplified tumor cells are more sensitive to PLK1 inhibitor treatment than tumors with normal N-Myc copy numbers." (PMID 36770809, 2023). "Given the potent role of PLK1 in sustaining tumor growth and mediating KRASG12Ci resistance, PLK1i would serve as both a pharmacological means to interrogate the dependence on PLK1 kinase activity and a promising point for a potential drug combination campaign." (PMID 38104151, 2023). "Furthermore, the in vivo antitumor efficacy of EGFR‐functionalized LNPs (targeting the PLK1 gene) was carried out in the OV8‐mCherry tumor model in mice." (PMID 37166046, 2023). "Additionally, the role of PLK1 in LA cell proliferation was confirmed through nude mouse transplantation tumor experiments, where tumor growth was significantly slower after PLK1 silencing than before." (PMID 37744268, 2023). "In conclusion, PLK1 may not only regulate tumor development, growth, and metastasis, but may also have substantial immunological implications in tumors." (PMID 36951624, 2023). "PLK1 protein expression levels were significantly increased in tumor tissues." (PMID 37415742, 2023). "PLK1 inhibitors have a favourable safety and tolerability profile making them ideal for combination treatment with traditional chemotherapy agents, or as long-term treatment to prevent tumour progression." (PMID 37648284, 2023). "Likewise, analysis of the IHC images of healthy breast tissues and tumor tissues in HPA also showed a tendency of higher PLK1 expression in the tumors, although there was sample variability, as well as discrepancies in picture quality." (PMID 38186570, 2023). "Additionally, nude mouse transplantation tumor experiments demonstrated that silencing PLK1 reduced the growth capacity of LA cells." (PMID 37744268, 2023). "In addition, PLK1 is also involved in the immune process, PLK1 can change the tumor immune microenvironment because it can promote cell proliferation and epithelial mesenchymal transformation and can also increase DC maturation and rich T cell infiltration." (PMID 36605099, 2022). "Similarly, PLK1 inhibitor volasertib significantly inhibited tumor proliferation, prolonged the survival of animals, and increased the infiltration of M1 macrophages in tumor region in our mouse model of intracranial xenograft tumors." (PMID 36618405, 2022). "It has been reported that, equipped with amino-ionizable lipid nanoparticles, Cas9 mRNA and sgRNAs targeting PLK1 could be effectively delivered into aggressive orthotopic glioblastoma, and inhibit the tumor growth." (PMID 35277177, 2022). "Consequently, we show that the combination of PLK1 inhibitor and PD-L1 antibody significantly reduces tumor progression in mice compared to each drug alone." (PMID 35871223, 2022).
tumor (continued). "Further research also showed that high PLK1 expression was related to shorter metastasis-free survival and poor response to endocrine therapy in hormone-receptor-positive breast cancer, whereas PLK1 inhibition resulted in tumor shrinkage and acquired palbociclib resistance." (PMID 36393842, 2022). "PLK1 expression levels were significantly correlated with tumor stage and size (P < 0.05)." (PMID 35756492, 2022). "Enrichment analysis of PLK1 related genes implied that PLK1 might promote tumor genesis and development by affecting antitumor immune in pan-cancer." (PMID 36618405, 2022). "In contrast, PLK1 inhibitors act on multiple stages of cell mitosis, such as blocking centrosome maturation, spindle formation, and cytokinesis, thereby disrupting cell division and cycle progression and ultimately leading to tumor cell death." (PMID 35756492, 2022). "Polo-like kinase 1 (PLK1) was closely related to cell cycle regulation and could accelerate the proliferation and progression of tumor cells." (PMID 36355508, 2022). "The enhanced anti-tumor efficacy of SN38 could be explained by the additional inhibition of PLK1, which is triggered by dasatinib." (PMID 36080304, 2022). "Enrichment analysis of PLK1 related genes showed that PLK1 might promote tumor genesis and development by affecting genetic alterations." (PMID 36618405, 2022). "HMN-214 significantly inhibits NB proliferation, induces apoptosis, inhibits cell cycle regulators, inhibits NB 3D spheroid tumor growth, and directly inhibits the phosphorylation and activation of PLK1 in NB to block the cell cycle progression at the G2/M phase." (PMID 35631350, 2022). "An increasing number of studies have shown that PLK1 is dysregulated in tumor tissues 40-43." (PMID 36439881, 2022). "In addition, Plk1 transgenic mice that express Plk1 in a graded manner had a shorter lifespan than wild-type mice due to increased tumor incidence." (PMID 35379935, 2022). "Among the multiple approaches blocking c‐Myc oncogenic activity, PLK1 inhibition by selective compounds, such as BI 2536 and BI 6727 (Volarsetib), represents an attractive therapeutic strategy in the treatment of c‐Myc‐driven tumours." (PMID 36054794, 2022). "Moreover, depletion of PLK1 in BC cells has been demonstrated to arrest cell cycle and tumor cell apoptosis." (PMID 35456552, 2022). "Moreover, we further analyzed the differential expressions of PLK1 mRNA between tumor tissues and normal tissues using the TCGA and GTEx databases with SangerBox." (PMID 36618405, 2022). "The circular RNAs derived from PLK1 locus also have important roles in tumor biology." (PMID 35114891, 2022). "Furthermore, cells surviving PLK1 inhibition have decreased tumorigenic potential, and targeting PLK1 in already established tumours reduces tumour growth both in cell line- and patient-derived xenograft models." (PMID 36008466, 2022). "The expression of these ten target genes was significantly upregulated in the tumor tissues compared to the adjacent normal tissues, and three of them (PLK1, CDK1, TOP2A) were also marked as landmark genes in CMap, which means these genes were widely expressed across the lineage." (PMID 35326724, 2022). "Therefore, PLK1 has recently emerged as a potential therapeutic target, mainly in tumours overexpressing c‐Myc." (PMID 36054794, 2022). "And PLK1 inhibitor volasertib can promote M1 macrophages infiltration to tumor region in vivo." (PMID 36618405, 2022). "Although the PLK1 mutation is documented in dbSNP (rs1004523813), it was not excluded from our analyses as the mutation is tumor specific (not present in paired NAT) and is very rare in the population (minor allele frequency <0.01)." (PMID 35367648, 2022). "Moreover, the protein levels of these three genes were detected using the human protein atlas (HPA) database, and the result showed the significant higher expression of CHMP4A, HMGB1 and PLK1 in the tumor tissues than in the normal ones." (PMID 36267972, 2022).
tumor (continued). "However, by using an inducible knock-in mouse model, a recent study also showed that PLK1 acts as a tumor suppressor." (PMID 34775484, 2022). "Plk-1 was overexpressed in tumor cells, disruption of which can lead to tumor apoptosis." (PMID 35918694, 2022). "In addition, in a mouse model of pancreatic ductal adenocarcinoma (PDAC), Plk1 silencing was shown to synergize with microRNA 34a (miR-34a), via the downregulation of the activated pathway, resulting in tumor growth inhibition." (PMID 34959480, 2021). "In this study, we found that inhibiting PLK1 could alter the tumor immune microenvironment by increasing DC maturation, and enriching T cells infiltration." (PMID 34522178, 2021). "However, there is now increasing evidence that PLK1 can also act as a tumor suppressor when expressed in the context of specific tumor types." (PMID 34605140, 2021). "Contrary, PLK1 levels are high in actively proliferating cells and tissues like testis, bone marrow, spleen or thymus, during embryonic development and, of special interest, in tumor cells." (PMID 34065956, 2021). "The images showed that the PLK1 inhibition group grew smaller neoplasms than the control group." (PMID 34779401, 2021). "To this end, we compared methylation of promoters of Plk1 in normal and tumor samples from TCGA." (PMID 34051063, 2021). "Moreover, high mRNA and protein expression levels of Plk1 have been detected in proliferating cells such as tumor cells." (PMID 34575464, 2021). "Plk1 is a driver of tumor growth orchestrated by the HIF-2 oncogenic pathway." (PMID 33547392, 2021). "The expression of EGFR and PLK1 mRNA was compared in normal and tumor tissues of LUAD patients." (PMID 34503223, 2021). "Inhibition of PLK1 significantly increases the survival of mice bearing ACHN OIP5 tumor." (PMID 34503297, 2021). "Since two distinct EBNA2 mutants that both target independent PLK1‐related functions of the EBNA2/PLK1 complex promote cancerogenesis, we conclude that PLK1 might act as a tumor suppressor in EBNA2‐driven lymphomagenesis." (PMID 34605140, 2021). "Furthermore, upon targeting PLK1, tumor cells that had undergone ICD were converted into an endogenous vaccine, which triggered the immune memory responses and protected the mice from tumor challenge." (PMID 34522178, 2021). "Furthermore, the results of qRT-PCR revealed that circ-ZNF609 and PLK1 expression were increased in the tumor tissues of the LV‐circ-ZNF609 group, while miR‐1224-3p expression was significantly decreased." (PMID 33976745, 2021). "Indeed, targeting of PLK1 with volasertib demonstrates anti-tumour effects against DMG cell lines in vitro, where it leads to significant cell cycle arrest and apoptosis." (PMID 34944870, 2021). "However, in tumor cells, Plk1 deregulation inhibits the activity of checkpoint actors, maintains cell cycle activity, promotes chromosomal instability and tumorigenesis." (PMID 34646387, 2021). "In addition to its tumor promoting role, Plk1 drives resistance to TKI and appears as a key target for a subgroup of metastatic ccRCC patients in therapeutic impasses." (PMID 33547392, 2021). "ARV-825 may have a good antitumor effect on PLK1 high expression tumor; how ARV-825 downregulate PLK1 is our subject in the following study." (PMID 34733788, 2021). "Plk1 also interacts with tumor suppressors presented as “guardians of genome”." (PMID 34646387, 2021). "This indicates that PLK1 acts as a tumor suppressor in EBV‐driven carcinogenesis." (PMID 34605140, 2021). "Data analysis yielded five drugs that emerged as potential candidates due to their superior efficacy in tumor cells: paclitaxel, d-actinomycin, volasertib (PLK1 inhibitor), navitoclax (BCL-2/BCL-XL/BCL-w inhibitor) and I-BET-151 (a Bromodomain family inhibitor) (online resource)." (PMID 34417833, 2021). "E2F and FoxM1, two transcription factors regulate Plk1 expression 33, 34, thus they could be closely related to Plk1-dependent tumor development." (PMID 34646387, 2021).
tumor (continued). "Knockdown of PLK1 alone did not significantly change the number of colonies formed, but instead it mitigated the increased colony formation observed following PLK2 knockdown, thus suggesting that the tumor suppressive function of PLK2 is specifically related to PLK1 activity." (PMID 35156101, 2021). "With uMUC1-specific ligand, EPPT1 and the myristoylated polyarginine peptide ligand and dextran, superparamagnetic iron oxide nanoparticle uptake was specific to pancreatic cancer and induced a drastic decrease in tumor volume in a syngeneic orthotopic model driven by PLK1 silencing." (PMID 34683931, 2021). "Targeting Plk1 inhibited tumor and endothelial cell proliferation in mice models." (PMID 33547392, 2021). "Notably, overexpression of PLK1 correlated positively with Dukes stage, tumor stage and nodal status." (PMID 34065438, 2021). "Cell cycle regulation is generally believed to be the principal mechanism of PLK1-inhibition in antitumor therapy, but whether it impacts tumor immunity in vivo is still unknown." (PMID 34522178, 2021). "In our study, we observed that Ili-A could reduce EZH2 protein and mRNA level and the expression of the downstream AURKA/PLK1 gene, which contribute to the anti-tumor effects against CRPC." (PMID 34776951, 2021). "Moreover, siRNA targeting tumor-related genes such as polo-like kinase-1 (PLK-1) can be loaded within MSC-derived exosomes for intravesical therapy." (PMID 33670202, 2021). "Additionally, a high level of PLK1/p‐PLK1 was correlated with a higher tumor recurrence rate (p < 0.001) and a shorter overall survival (OS) time (p < 0.001)." (PMID 34881526, 2021). "PLK1 blockade reportedly could lower the expression of Myc in tumor cells, since Myc inactivation has been demonstrated to induce the down-regulation of PDL1, an immunosuppressive molecule 39-42, which was identified as the major trigger of T cell exhaustion." (PMID 34522178, 2021). "The PLK1, PhosphoMet, SGK2, and SHC1 IHC staining of tumor samples from high-risk (disease progression) patients mostly showed low cytoplasmic expression, while tumor samples from low-risk (progression-free) patients mostly showed high cytoplasmic expression." (PMID 34575686, 2021). "This represents another mechanism, where elevated PLK1 activity has an essential function in tumor cells and could provide a targetable vulnerability." (PMID 33066048, 2020). "PLK1 (polo like kinase 1) is a highly conserved serine/threonine protein kinase widely existing in eukaryotic cells with diverse functions of regulating cell cycle, inhibiting tumor cell apoptosis and promoting tumor formation." (PMID 33354424, 2020). "However, if PLK1 overexpression contributes to tumour formation, by inducing mitotic alteration and chromosomal instability, is still a matter of debate." (PMID 32438775, 2020). "The imbalance between PLK1 and tumor suppressor protein may accelerate the progression of the tumor." (PMID 32848800, 2020). "Since PLK1 overexpression contributes to tumor heterogeneity, targeting SDL interactions may also provide an effective strategy to suppressing this malignant phenotype in a personalized fashion." (PMID 33066048, 2020). "Intravenous injection of PEGylated lipid shells encapsulating plasmid DNA into A375 tumor-bearing mice was found to reduce expression of PLK1 in tumor tissues and provide greater antitumor effects compared to treatment with a lipoplex of plasmid DNA and the commercial agent, Lipofectamine 2000." (PMID 33353099, 2020). "Moreover, the treatment of αHB-EGF LNP-siPLK-1 in mice yielded lower PLK-1 protein levels and tumor growth as compared to control groups." (PMID 32580326, 2020). "This could be explained by the decreased expression of PLK1 in fulvestrant-treated tumours, consistent with published data showing that fulvestrant downregulates genes associated to cell proliferation and mitosis." (PMID 32792481, 2020).
tumor (continued). "Meanwhile, ZNF300 might activate CDK1 through inhibition of WEE1 and MYT1 and modulation of the MYC/AURKA/BORA/PLK1 axis to promote the tumour cells to overcome G2 arrest and enter the M phase to avoid the apoptosis induced by chemotherapeutic drugs." (PMID 33078469, 2020). "The results from this study support the hypothesis that aberrant expression of PLK1 leads to the inhibition of the tumor suppressor function of FOXO1, thereby contributing to PCa survival and/or resistance to therapy." (PMID 32704044, 2020). "Thus, PLK1 activity is needed to induce tumor formation and metastasis, which was effectively blocked by specific the inhibitor volasertib in both an animal model and our cell-based 3D-culture system." (PMID 31548612, 2020). "Next, we evaluated whether PLK1-based peptide vaccination would offer a therapeutic benefit in vivo against established syngeneic tumours." (PMID 32595211, 2020). "PLK1 is considered as an attractive target for tumor intervention therapy." (PMID 32848800, 2020). "Furthermore, inhibition of PLK1 blocked the growth of CD44 high/CD24-/low tumour-initiating cells in TNBC." (PMID 32050983, 2020). "More importantly, PLK1 plays a more critical role in tumor development." (PMID 32848800, 2020). "Furthermore, blocking the expression of PLK1 can effectively inhibit the proliferation of tumour cells and induce their apoptosis." (PMID 32463161, 2020). "Similarly to Plk1, Plk4 was recently found to be aberrantly expressed and involved in tumor progression." (PMID 32060361, 2020). "In this aspect, our findings provide a promising preclinical strategy in which using PLK1-derived CD8 T-cell epitope peptides one could achieve high levels of tumour-reactive T-cell responses eliciting potent therapeutic effects." (PMID 32595211, 2020). "To date, only PLK1 was identified as an important coordinator of glucose metabolism in tumor cells." (PMID 31655629, 2019). "Upregulation of Plk1 has been reported in several tumor types, including NSCLC." (PMID 31795121, 2019). "Blocking the expression or action of PLK1 can effectively inhibit the proliferation of tumor cells." (PMID 31437238, 2019). "On one hand, in addition to the block of mitotic progression, the centromere-specific damage induced by PLK1 inhibition might trigger further catastrophic mitotic responses in tumor cells, thus enhancing the efficacy of PLK1 inhibitor treatments." (PMID 31692966, 2019). "Polo-like kinase 1 (PLK1) gene is recognized as a key regulator of tumor cell meiosis and mitosis." (PMID 31681729, 2019). "Whereas, complete depletion of Plk1 is incompatible with embryonic development, stopping mouse embryos at the morula stage, Plk1 heterozygous mice are compatible with life and are tumor-prone." (PMID 30862113, 2019). "Thus, while our model system further supports the concept of using PLK1 inhibitors to target MYC-driven tumours, important next steps will be testing this mechanism in more clinically relevant contexts." (PMID 31455158, 2019). "Therefore, we evaluated the anti-tumor effect by direct injection into KB tumor xenografts with LP-HAPC-2mol%FA-PEG2000 lipoplexes of PLK1 siRNA." (PMID 30991703, 2019). "Although E2F and FOXM1 are closely related to oncogenic processes, Plk1 regulation in tumors that are driven by any of these transcription factors might merely recapitulate the higher proliferation index within the tumor." (PMID 30862113, 2019). "To examine whether transfection of PLK1 siRNA into KB cells with FA-PEG modified siRNA lipoplexes could selectivity inhibit tumor growth, we measured cell viability 48 h after transfection of PLK1 siRNA into KB cells." (PMID 30991703, 2019). "In addition, pre-clinical studies using small interfering RNAs (siRNA) inhibited PLK-1 resulting in the G2/M arrest, apoptosis and tumor growth inhibition." (PMID 30733560, 2019).